RN7SL757P (RNA, 7SL, cytoplasmic 757, pseudogene)
Gene: Miscellaneous RNA gene on chromosome 22 (28,056,153 to 28,056,453, reverse strand). Ensembl gene ENSG00000239249.
Homologues: Orthologues: chimpanzee Metazoa_SRP (99% identical), macaque Metazoa_SRP (95% identical). Paralogues in human: RN7SL1 (79% identical), RN7SL2 (79% identical), RN7SL45P (79% identical), RN7SL220P (78% identical), RN7SL3 (77% identical), RN7SL709P (77% identical), RN7SL122P (77% identical), RN7SL127P (77% identical), RN7SL479P (77% identical), RN7SL113P (76% identical), RN7SL786P (76% identical), RN7SL126P (76% identical), and 705 more.